AXL (AXL receptor tyrosine kinase)
Diseases named in the same sentence as AXL in open-access papers (continued):
Sharing a sentence is not in itself a finding about the gene and the disease.
tumor (continued). "Although the mechanism of action of EnaV is dependent on AXL expression, it acts independently of activation of AXL/Gas6 signaling, with tumor cell death being driven by MMAE interference with cell division." (PMID 41166388, 2025). "AXL is also expressed on innate immune cells and promotes an immunosuppressive tumor microenvironment." (PMID 40122885, 2025). "In leukaemia, AXL is induced by tumour-derived GAS6, which also acts on NK cells to reduce NKG2D expression and impair cytotoxicity." (PMID 40948757, 2025). "This was also confirmed by qRT‐PCR with significant upregulation of fibronectin (FN1), fascin (FSCN1), and the receptor tyrosine kinase AXL, which has been associated with EMT, tumor cell invasion, and therapy resistance in different tumor entities." (PMID 40066744, 2025). "Immunoblotting assay was performed to confirm the protein level of STAMBPL1, TRIM21 and AXL in excised orthotopic tumor." (PMID 39527690, 2025). "This synergy is mechanistically plausible, as paclitaxel-induced immunogenic cell death increases tumor visibility to the immune system, while AXL inhibition relieves immune suppression and promotes NK cell activation." (PMID 41009462, 2025). "AXL expression correlates with enhanced tumor cell migration and invasion, and its inhibition is being explored as a potential therapeutic approach in EMT-driven MPM." (PMID 40277909, 2025). "This dual role, supporting both tumor cell survival and immune evasion, makes AXL an appealing target for therapeutic intervention." (PMID 41009462, 2025). "AXL is a receptor tyrosine kinase with a critical role in tumor progression, metastasis, and resistance to chemotherapy." (PMID 41347223, 2025). "TYRO3 expression was rarely detected, while AXL was expressed in myeloid cells, tumor epithelial cells, and CAFs." (PMID 40433916, 2025). "By targeting AXL, ADCs can potentially deliver cytotoxic agents directly to tumor cells while minimizing damage to normal tissues." (PMID 41347223, 2025). "To investigate TIC-derived GAS6 suppression of tumor immunity via AXL/MERTK on Reg-TAMs, we used Krt19-DreER Axin2-creER R26-Ai66 mice for AKT/YAP/SB hydrodynamic injection and sorted Reg-TAMs and epithelial cell adhesion molecule+/Tom+ (EpCAM+Tom+) TICs." (PMID 39774471, 2025). "AXL is known to be involved in tumor cell growth, metastasis, and drug resistance and has been shown to bind to members of the EGFR and HER families, including MET, to promote EGFR signaling and contribute to EGFR-TKI resistance." (PMID 40224214, 2025). "Currently, there is proof that the excessive production of AXL is responsible for the development of resistance to chemotherapy in multiple tumour models." (PMID 40088262, 2025). "Research has demonstrated that the Gas6/AXL signalling pathway plays a crucial role in promoting the survival, proliferation, mobility, and invasion of tumour cells." (PMID 40088262, 2025). "Using the ESTIMATE algorithm, we analyzed tumor purity and found that the high-AXL expression group had significantly increased ESTIMATE scores, immune scores, and stromal scores." (PMID 41029360, 2025). "The AXL/GAS6 axis is highly expressed in tumor cell lines and BC tissues and contributes to critical processes such as proliferation, apoptosis, survival, migration, inflammation, and angiogenesis." (PMID 40281554, 2025). "Further investigations exploring drug delivery to the tumor site, alternative methods, and combination therapies are needed to assess the potential of AXL as a target for the treatment of solid tumors." (PMID 41166388, 2025). "GAS6 was the only well‐characterized Gla protein that regulated oncogenic signalling pathways through binding to and activating Axl receptor tyrosine kinase on tumour cells, which was overexpressed in several types of cancer." (PMID 39843398, 2025). "MZF1 promotes various types of cancers by targeting key regulators of tumor progression, including c-Myc, AXL, IGF1R, and PKCα." (PMID 40961095, 2025).
tumor (continued). "Specifically, disruption of the STAMBPL1/AXL axis will provide therapeutic benefits by reducing mesenchymal phenotypes and enhancing tumor immunogenicity." (PMID 39527690, 2025). "In metastatic ovarian serous adenocarcinoma, AXL overexpression by immunohistochemistry (IHC) has been demonstrated in 88% of primary tumours, 75% of omental, and 90% of peritoneal deposits." (PMID 40696160, 2025). "On the other hand, AXL is another emerging potential therapeutic target in various cancers due to its effect in promoting cell proliferation, invasion and migration, and tumor growth." (PMID 40725039, 2025). "AXL inhibition alters the components of the tumor immune microenvironment, such as the number of DCs and CD8+ T cell infiltration." (PMID 40959280, 2025). "Beyond its established role in driving tumor proliferation, migration, and metastasis, AXL also promotes immune evasion by modulating the tumor microenvironment." (PMID 41009462, 2025). "For these reasons, tumor AXL expression was assessed retrospectively to determine its potential as an enrichment biomarker." (PMID 41166388, 2025). "Functional AXL present in the dendritic cells supported tumour growth via immune checkpoint inhibition." (PMID 40044635, 2025). "Accumulating evidence suggests that AXL activation shapes an immunosuppressive tumor microenvironment." (PMID 38310091, 2024). "Recently, increasing evidence suggests that AXL activation shapes an immunosuppressive tumor microenvironment." (PMID 39598377, 2024). "It is known that G12D‐mutated tumor cells can signal oncogenic stimuli to stromal cells, the later promoting IGF1R, AXL and AKT signaling and providing a high level of complexity." (PMID 38650175, 2024). "Dysregulation of AXL was also found in tumor cells, fibroblasts, vascular cells, and various immune cells." (PMID 38391974, 2024). "AXL expression is also correlated with acquired MAPK resistance, including BRAFi/MEKi double resistance, and targeting AXL cooperatively inhibited tumor growth with BRAF/MEK inhibitors in patient-derived xenografts." (PMID 38732242, 2024). "On one hand, AXL is upregulated by tumor cells in response to antitumor immunity and induces PD-L1 expression, priming tumors to initially respond to ICIs." (PMID 39238637, 2024). "As a final step, we evaluated the antitumor activity by combining DSP-0509 and the AXL inhibitor in an in vivo tumor model, which demonstrated increased efficacy." (PMID 39346737, 2024). "Surprisingly, we found differences in the predictive value of tumor- versus immune-AXL expression that correlated with distinct oncotypes and TME immune-profiles associated with ICI prognosis." (PMID 39238637, 2024). "Inhibitors 22 and 33 demonstrated strong in vitro with both MER and AXL at nanomolar levels and in vivo potent efficacy in both syngeneic and mouse models as well as humanxenograft tumor models." (PMID 38913493, 2024). "Using SPECT/CT imaging, we observed tumor uptake of 99mTc-sdAb20 in mice with AXL-positive THP-1 or C1498 tumors." (PMID 38773967, 2024). "In this regard, the expression of the receptor tyrosine kinase AXL was correlated with poor survival in a wide range of malignancies, and it is becoming clear that this receptor plays a significant role in tumor growth and spread." (PMID 38391974, 2024). "Future analysis on the role of AXL in the tumor microenvironment should therefore discriminate between the different cell types expressing AXL." (PMID 39697983, 2024). "Efferocytosis-related receptors, such as MerTK and AXL, have been found to play a role in promoting tumor progression." (PMID 38802814, 2024). "Activated AXL leads to a significant increase in tumor proliferation, tumor cell migration, and angiogenesis in different in vitro and in vivo models of cancer since this receptor regulates interplay with apoptotic, angiogenic and inflammatory pathways." (PMID 38391974, 2024).
tumor (continued). "Whole-exome sequencing (WES) was performed on 44 tumor samples from the whole AXL-IHC cohort, with a similar distribution of clinical and molecular features." (PMID 39238637, 2024). "With the in-depth study of AXL, it has been found that AXL can become a rising star of cancer therapeutic targets, and some NSAIDs are able to target AXL to achieve anti-tumor effects." (PMID 39598398, 2024). "Considering the evidence of TAM family involvement in cancer progression, clinical development of inhibitors targeting TAM members, including AXL, is currently underway as potential anti-tumor therapeutics." (PMID 39346737, 2024). "We analyzed the evolution of genomic alterations and the levels of AXL using tumor specimens obtained by repeated biopsies during the course of treatment: initial diagnosis, operation, and disease progression." (PMID 38323355, 2024). "Initially, we assessed the mRNA and protein expression levels of PROS1 and AXL across various human tumor types using the Human Protein Atlas (HPA) database." (PMID 38254761, 2024). "Activation of AXL often accompanies the occurrence of tumor cell EMT, promoting resistance of NSCLC cells to EGFR TKIs." (PMID 39582541, 2024). "GAS6 is a vitamin-K-dependent growth factor expressed by several cells like monocytes, endothelial cells, brain, heart, fibroblast, and tumor cells and has the best affinity for AXL among all the TAM family members." (PMID 38391974, 2024). "In cancer, AXL is expressed on tumor cells as well as adjacent immune cells (e.g., dendritic cells, macrophages), and is often considered as an inhibitor of the innate immune response." (PMID 38773967, 2024). "The critical role of AXL, a receptor tyrosine kinase, in promoting tumor cell survival, metastasis, and therapeutic resistance is well established." (PMID 39273190, 2024). "•Tumor heterogeneity is a hurdle to effective therapy, illustrated by the resistance of AXL+ tumor cells to targeted therapy." (PMID 39697983, 2024). "We provided a distinct and HCC-specific mechanism of AXL-driven tumor-intrinsic signaling to promote an immunosuppressive phenotype of TKI-resistant HCC and further proposed the application of AXL targeting to overcome a potential cross-resistance in HCC." (PMID 38310091, 2024). "Emerging data from the literature show that AXL+ tumor cells contribute to increased resistance to targeted therapy, including mitogen-activated protein kinases inhibitors." (PMID 39697983, 2024). "Previously, AXL+ tumor cells were identified to be highly resistant to targeted therapy, whereas more differentiated MITF+ tumor cells do respond to RAF and MEK inhibitors." (PMID 39697983, 2024). "Regulating AXL is crucial for tumor development and neovascularization and is an important therapeutic target for metastatic cancer cells." (PMID 39451232, 2024). "The GAS6/AXL pathway influences drug resistance through interactions with other signals and regulation of the tumor microenvironment (TME)." (PMID 38539161, 2024). "We found that 1L-patients who required radiotherapy (RT) to achieve local tumor control in the thorax or to treat symptomatic bone metastases had higher AXL Hscores at diagnosis (P = 0.0049)." (PMID 39238637, 2024). "In summary, we identify that AXL inhibition plus WIN55212-2 treatment exhibited synergistic anti-tumor effects in vitro and in vivo." (PMID 39598377, 2024). "NPS-1034 inhibits multiple receptor tyrosine kinases (RTKs) implicated in tumor growth, metastasis, and angiogenesis, with targets including MET and AXL." (PMID 39451232, 2024). "In our study, the AXL inhibitor bemcentinib, that was included as a positive control, clearly demonstrated also AXL-independent anti-tumor effects in vitro." (PMID 38773967, 2024). "Of interest, we observed discernibly higher AXL expression in tumor cells at operation in both patients, which is highly consistent with our previous reports showing that AXL plays crucial role for emerging osimertinib tolerant cells." (PMID 38323355, 2024).
tumor (continued). "In this review, we will mainly introduce the role of the Gas/AXL signaling in cancer cells, discuss its interaction with the tumor immune microenvironment, and its relationship with tumor progression." (PMID 37265798, 2023). "While EGFR kinase inhibitors (EGFR–TKIs) are widely used and efficacious in treatment, increases in resistance and tumor recurrence with alternative survival pathway activation, such as that of AXL and MET, occur frequently." (PMID 37834326, 2023). "Expression of these genes was validated using immunohistochemistry or immunofluorescence staining in both PDCs and respective tumor tissue, and this was recapitulated on flow cytometry for AXL (HN137) and AURKB (HN159 and HN220)." (PMID 36973261, 2023). "AXL has also been shown to contribute to tumour progression in metastasis and the acquisition of drug resistance via the activation of pathways such as MAPK/Erk and PI3K/Akt signalling." (PMID 37349576, 2023). "In this regard, sunitinib resistance can induce compensatory overexpression/activation of the receptor tyrosine kinases MET and AXL, as well as their transduction signaling in tumor cells." (PMID 36982721, 2023). "In contrast to other multi–tyrosine kinase inhibitors, cabozantinib targets VEGFR-1–3 as well as MET and the tumor-associated macrophage (TAM) family (TYRO3, AXL, and MER) of receptor kinases." (PMID 36982920, 2023). "AXL is highly expressed in a variety of tumor types, including ovarian, breast, lung and renal cancers, and its expression correlates with poor patient survival through the regulation of invasion, metastasis, drug resistance and immune suppression." (PMID 36980768, 2023). "More importantly, AXL knockdown significantly reduced subcutaneous tumor growth of both cell lines in mice." (PMID 36980768, 2023). "Flow cytometry showed different AXL expression levels on the surface of tumor cells: high expression on CAL-72, ESS-I and HT-1080; intermediate expression on SAOS-2 and Rh-30; and low- or no-expression on SW982 and RD-ES cell lines, respectively." (PMID 36980534, 2023). "The role of AXL in EGFR inhibition resistance was established by analysis of AXL expression in tumor xenograft mice and in CRC patients after anti-EGFR treatment." (PMID 37469409, 2023). "C7R activates the IL-7 signaling axis without needing extracellular cytokines and enhances the anti-tumor activity of anti-AXL CAR T-cells in TNBC models." (PMID 38201551, 2023). "Li and collaborators observed that Gas6 interaction with AXL induced tumor cell migration mostly by upregulating Slug in prostate and skin cancer cells." (PMID 37265798, 2023). "AXL inhibition by using R428 attenuated the expressions of phosphorylated AXL (pAXL) and the downstream phosphorylated Erk (pErk), significantly impaired cell motility and suppressed in ovo tumour formation." (PMID 37349576, 2023). "AXL is another promising target for therapy; in preclinical models inhibition of AXL by an antibody-conjugated drug blocked tumour growth." (PMID 37795454, 2023). "AXL (a member of the Tyro3-Axl-Mer/TAM family) is a receptor tyrosine kinase and is activated by binding to its ligand GAS6 (growth arrest specific 6); the GAS6/AXL pathway promotes tumor progression in part by facilitating immune evasion." (PMID 36588164, 2023). "VGFR3 and AXL were significantly downregulated in tumours compared with healthy livers from healthy individuals." (PMID 36890818, 2023). "The Gas6/AXL pathway regulates angiogenesis, immune-related molecular markers and the secretion of certain cytokines in the tumor microenvironment, and also modulates the functions of a variety of immune cells." (PMID 37265798, 2023). "More specifically, AXL has been shown to be involved in cell proliferation, survival, tumor metastasis, stem cell phenotype, and more importantly, therapy resistance." (PMID 36835239, 2023).
tumor (continued). "Preclinical data demonstrated inhibition of Gas6-induced AXL and Src phosphorylation, tumor vessel density, tumor growth, and metastatic burden in renal cell carcinoma and ovarian cancer in response to treatment with AVB-500." (PMID 37469409, 2023). "Pre-clinical studies have demonstrated anti-tumour activity of AXL-targeted CAR T-cells, either alone or in combination with tumour-targeted microwave ablation." (PMID 36831514, 2023). "This further demonstrates an important role for the AXL pathway in tumor cell migration and invasion." (PMID 37265798, 2023). "This open-label, phase 1 study provided novel findings regarding the safety and tumor response of DS-1205c, a kinase inhibitor that selectively targets AXL, in combination with osimertinib in 13 patients with metastatic or unresectable EGFR-mutant NSCLC." (PMID 36892745, 2023). "Tumor samples from 11 patients underwent AXL immunohistochemistry evaluation; tumor tissue was insufficient to evaluate by immunohistochemistry for the remaining 2 patients (1 each in cohorts 2 and 3)." (PMID 36892745, 2023). "Quercetin has been shown to inhibit proliferation in several cancer cell lines, and one study found that quercetin had anti-tumor activity in NSCLCs harboring wild-type EGFR by inhibiting AXL and inducing apoptosis." (PMID 36959600, 2023). "As Gas6/AXL signaling triggers an immunosuppressive tumor microenvironment, the functions of diverse immune cells and the overall makeup of the tumor immune microenvironment are modified in this process." (PMID 37265798, 2023). "The MDK/LRP1, MDK/ALK, GAS6/MERTK, and GAS6/AXL were identified as potential ligand-receptor pairs involved in the interactions between fibroblasts/endothelial cells and tumor cells." (PMID 37733241, 2023). "Further, our results identified potential ligand-receptor pairs (MDK/LRP1, MDK/ALK, GAS6/MERTK, and GAS6/AXL) for cell communication between these two types of cells and tumor cells." (PMID 37733241, 2023). "Given the role of AXL in cancer growth and metastasis as well as its relatively low expression in normal tissues compared with tumor tissues, AXL represents a highly potential therapeutic target in cancer therapy." (PMID 37265798, 2023). "The role of AXL in tumor-cell invasion and migration was also confirmed using Matrigel-coated invasion chambers and scratch assays." (PMID 36980768, 2023). "A recent study demonstrated that OS cells with high AXL expression promoted growth, invasion, and metastasis of tumor cells with low AXL expression through releasing linc00852-containing exosomes." (PMID 36982236, 2023). "Differences in tumor weight between shScrambled and shAXL tumor tissues further support that inhibition of AXL expression decreased tumor growth." (PMID 36980768, 2023). "Inhibition of AXL using small molecule inhibitors or silencing AXL via short-hairpin knockdown systems was able to prevent tumour progression and to re-sensitise treatment-resistant cancer cells, making it an emerging therapeutic target." (PMID 37349576, 2023). "Although there are mixed results regarding the action of AXL in primary tumor growth, our data showed that knocking down AXL inhibited cell growth in vitro and tumor growth in vivo." (PMID 36980768, 2023). "Previous studies found that miR-34a-5p is significantly reduced in CAF-Exos, which directly upregulates AXL and further promotes tumour progression by increasing the activation of SNAIL." (PMID 37668846, 2023). "In ovarian and uterine cancer models, siRNA targeting AXL, a driver of tumor cell motility and metastasis, was administered intraperitoneally to suppress tumor nodule number and mass." (PMID 37298407, 2023). "It plays an essential role in tumor progression in various cancers, which is regulated by many key signaling pathway, such as c-Met, AXL, or TRK, etc.." (PMID 37945598, 2023).